EXPH5 (exophilin 5)
Description:
May act as Rab effector protein and play a role in vesicle trafficking.
Synonyms: SlaC2-b; SLAC2B; EBS4
Tractability: PROTAC: ubiquitination databases record sites on it.
Gene: Protein-coding gene on chromosome 11 (108,505,435 to 108,593,768, reverse strand). Ensembl gene ENSG00000110723.
Subcellular location (Human Protein Atlas): Cytosol
Gene Ontology:
Molecular function: small GTPase binding
Biological process: keratinocyte development; multivesicular body sorting pathway; positive regulation of exocytosis; positive regulation of protein secretion; intracellular protein transport
Cellular component: endosome
Genetic constraint (gnomAD): Loss-of-function variants: 23 observed, 28.53 expected, observed/expected ratio (o/e) 0.81, 90% interval 0.58 to 1.14. The upper end of that interval is the gene's LOEUF score, 1.14, which puts it in group 5 of 6, group 1 being the genes least tolerant of losing a copy. Missense variants: 2,206 observed, 2,325.1 expected, observed/expected ratio (o/e) 0.95, 90% interval 0.92 to 0.98. Synonymous variants: 762 observed, 848.61 expected, observed/expected ratio (o/e) 0.9, 90% interval 0.85 to 0.95.
Homologues: Orthologues: chimpanzee EXPH5 (99% identical), macaque EXPH5 (94% identical), dog EXPH5 (69% identical), pig EXPH5 (67% identical), rabbit EXPH5 (59% identical), guinea pig EXPH5 (58% identical), mouse Exph5 (57% identical), rat Exph5 (56% identical), tropical clawed frog exph5 (18% identical).
Diseases named in the same sentence as EXPH5 in open-access papers:
EXPH5 is named in the same sentence as 9 diseases in open-access papers, as found by Europe PMC text mining. Sharing a sentence is not in itself a finding about the gene and the disease. The quoted sentences say what the papers report.
epidermolysis bullosa (6 papers, 2017 to 2026). Epidermolysis bullosa (EB) is a group of genetic skin diseases that cause the skin to blister very easily. "Mutations of the EXPH5 gene, which is highly expressed in podocytes, have been reported to play an important role in epidermolysis bullosa, a disease that can be associated with congenital nephrotic syndrome and FSGS." (PMID 39125467, 2024). "Significantly enriched keywords associated with our group of genes were Epidermolysis bullosa due to four genes with variants in our study group (EXPH5, PLEC, COL7A1, LAMB3)." (PMID 36454308, 2023). "NGS has also been used to identify novel genes in genodermatoses with well-established causes, such as the discovery of novel germline EXPH5 mutations in epidermolysis bullosa (EB)." (PMID 37841001, 2023). "Mutations in EXPH5 are associated with a disorder called epidermolysis bullosa, leading to skin fragility." (PMID 29297313, 2017). "Two additional patients presenting with epidermolysis bullosa harbored truncating variants in COL7A1 (c.497dup; p.Val168Glyfs12) and EXPH5 (c.5786del; p.Pro1929Leufs8), respectively; the latter also carried a KRT5 missense variant (c.1607G>A; p.Ser536Asn)." (PMID 42194992, 2026). "Other transcripts are likely related to follicular (Pla2g2e, Prss53) and keratinocyte (Exph5) adhesion and migration, and Pla2g2e has been specifically related to skin disorders such as epidermolysis bullosa and skin fragility." (PMID 34823472, 2021).
psychiatric disease (1 paper, 2024). "Within our dataset, genes with shifted aging trajectories in psychiatric disease include APLF (in Exc_L2–L3, Exc_L4–L6_1 and Exc_L4–L6_2 neurons), EXPH5 (in Exc_L2–L3 and Exc_L4–L6_3 neurons) and RHBDL3 (in Exc_L4–L6_2 neurons)." (PMID 39227716, 2024).
EXPH5 also shares sentences with these, for which no sentence is quoted: cancer (2 papers); tumor (2); breast carcinoma (1); cardiovascular disease (1); congenital nephrotic syndrome (1); skin disorder (1); skin fragility (1).